SNORA30B (small nucleolar RNA, H/ACA box 30B)
Gene: Small nucleolar RNA gene on chromosome 9 (20,786,927 to 20,787,055, forward strand). Ensembl gene ENSG00000202189.
Gene Ontology:
Biological process: RNA processing
Cellular component: nucleolus
Homologues: Orthologues: macaque SNORA30B (98% identical), chimpanzee SNORA30B (97% identical), dog SNORA30B (86% identical). Paralogues in human: SNORA37 (93% identical), SNORA30 (88% identical).